NLRP1 (NLR family pyrin domain containing 1)
Diseases named in the same sentence as NLRP1 in open-access papers (continued):
Sharing a sentence is not in itself a finding about the gene and the disease.
central nervous system disorder (1 paper, 2016). A disease involving the central nervous system. "While our current negative findings using a genetic approach were unexpected, they emphasize the need to further explore the clinical relevance and mechanistic details underlying the NLRP1 inflammasome in brain injury and other related central nervous system disorders." (PMID 27199506, 2016).
NLRP1 also shares sentences with these, for which no sentence is quoted: Addison’s disease (9 papers); pulmonary fibrosis (5); chronic obstructive pulmonary disease (4); multiple self-healing palmoplantar carcinoma (4); systemic sclerosis (4); acute kidney injury (3); autoinflammation with arthritis and dyskeratosis (3); cardiovascular diseases (3); chronic prostatitis (3); Crohn disease (3); heart failure (3); acute myocardial infarction (2); adenoma (2); Autoimmune Addison's disease (2); benign prostatic hyperplasia (2); bladder cancer (2); cerebral artery (2); chorioamnionitis (2); eczema (2); ischemia (2); lupus erythematosus (2); myocardial ischemia (2); pemphigus vulgaris (2); periodontal disease (2); psoriasis vulgaris (2); rectum adenocarcinoma (2); acute coronary syndrome (1); acute lung injury (1); Adrenal insufficiency (1); Adrenocortical Carcinoma (1).
A further 83 diseases each share a sentence with NLRP1 in 1 paper.